BAG3 (BAG cochaperone 3)
Diseases named in the same sentence as BAG3 in open-access papers (continued):
Sharing a sentence is not in itself a finding about the gene and the disease.
cardiomyopathy (continued). "We reidentified all five loci harboring Mendelian cardiomyopathy-linked genes found in prior common variant analyses of DCM (ALPK3, BAG3, FLNC, PLEKHM2, and TTN)." (PMID 32382064, 2020). "Because human BAG3 cardiomyopathy is an autosomal dominant disease, we acknowledge the limitation of using a homozygous bag3e2/e2 mutant to model this subtype DCM." (PMID 31492659, 2019). "The reading-frame-shift genotype of bag3e2/e2 mutants would most likely confer a loss of function, recapitulating genetic lesions in mammals that lead to BAG3 cardiomyopathy." (PMID 31492659, 2019). "This study established the bag3e2/e2 mutant as a DCM model in adult zebrafish and suggested mtor as a candidate therapeutic target gene for BAG3 cardiomyopathy." (PMID 31492659, 2019). "Together, these data provide strong genetic evidence to support mtor as a candidate therapeutic target for bag3 cardiomyopathy in zebrafish." (PMID 31492659, 2019). "In this study, we report the generation of bag3e2/e2 mutants in adult zebrafish to model BAG3 cardiomyopathy." (PMID 31492659, 2019). "Given that the bag3 cardiomyopathy model exhibited accelerated cardiac aging phenotypes, we then asked whether fabp7a inhibition affects cardiomyocyte senescence through immunostaining assays." (PMID 40922543, 2025). "In addition, the increased apoptosis index while reduced proteasome activity in the bag3 cardiomyopathy model were partially rescued by the fabp7ae1/+ haploinsufficiency mutation." (PMID 40922543, 2025). "We discuss the potential for additional avenues of therapeutic intervention with studies of ACE2 in hypertension and diabetes, and BAG3 in cardiomyopathies, and the need to understand the relationships with NT-proBNP for diagnostic purposes in stratified groups of patients." (PMID 41054850, 2025). "Recent studies suggest a strong association between BAG3 variants and cardiac fibrotic remodeling through TGF-β dysregulation, which may contribute to the development of cardiomyopathies." (PMID 41378130, 2025). "Cardiomyopathy genes, including nine prespecified DCM genes including BCL2-associated athanogene-3 (BAG3), desmoplakin (DSP), LMNA, MYH7, sodium voltage-gated channel, alpha subunit 5 (SCN5A), telethonin (TCAP), cardiac troponin C (TNNC1), TNNT2, and TTN, were sequenced." (PMID 40004816, 2025). "In the three patients, genetic diagnosis was made at a median of 3 years [3–4.5] after the onset of symptoms, by an exome for two of them and a targeted genetic analysis of BAG3 for patient three thanks to the medical staff knowledge of this particular BAG3 cardiomyopathy." (PMID 41378130, 2025). "In particular, BAG3 levels were decreased in both idiopathic (fold change = 0.646, adjusted p-value = 9.60 × 10−6) and ischemic (fold change = 0.633, adjusted p-value = 9.77 × 10−6) cardiomyopathies." (PMID 39457090, 2024). "If the same phenomenon is true in humans, the highlighted cell cycle proteins in this study may be implied for early intervention for cardiomyopathies, particularly for a BAG3-based therapy." (PMID 39457090, 2024). "BAG3 interactions with these upregulated genes in cardiomyopathies are interesting as this could ameliorate the cardioprotective effects of BAG3." (PMID 39457090, 2024). "Whereas mutations in ALPK3 have been associated with non-sarcomeric hypertrophic cardiomyopathy or dilated cardiomyopathy, BAG3 and RBM20 genes have been associated with dilated cardiomyopathy phenotype further highlighting a potential link between MVP and cardiomyopathy." (PMID 36873395, 2023). "As a result, myh9b was identified as a novel modifier gene for bag3 cardiomyopathy." (PMID 35481478, 2023). "Together, these data confirmed myh9b as a new modifier gene for bag3 cardiomyopathy." (PMID 35481478, 2023). "Thus, we can designate BAG3 as an important target for future therapeutic interventions for cardiomyopathy, various cancers and neurological disorders." (PMID 36980278, 2023).
cardiomyopathy (continued). "BAG3 has also recently emerged as a major cardiomyopathy gene." (PMID 33467574, 2021). "In addition to its physiological function, BAG3 is also involved in several pathological conditions, including cardiomyopathies, age-related neurodegenerative diseases, and cancer." (PMID 32121220, 2020). "This demonstrates that loss of Bag3 in our CRISPR/Cas9-induced zebrafish line does not cause cardiomyopathy and skeletal muscle dysfunction under physiological or stressed conditions." (PMID 33137814, 2020). "Whether mTOR inhibition is effective in ameliorating the BAG3 cardiomyopathy subtype remains untested." (PMID 31492659, 2019). "As a future direction, much milder phenotypes in the aged bag3e2/+ heterozygous mutant will be analyzed in more detail, which might be a more faithful model recapitulating human BAG3 cardiomyopathy." (PMID 31492659, 2019). "In addition to TTN and BAG3, MYBPC3 was present in the cardiomyopathy gene-set and harbored variants associated with sporadic DCM in our EWAS." (PMID 28296976, 2017). "Due to its roles in cardiomyopathies and the complexity of BAG3–protein interactions, it is important to understand these protein interactions given the importance of the multifunctional cochaperone BAG3 in cardiomyocytes, using an in vitro cardiomyocyte model." (PMID 39457090, 2024). "In addition, the BAG3 gene has also been reported to be associated with other diseases such as Takotsubo cardiomyopathy, HIV-associated cardiomyopathy, and virus-associated myocarditis, in which the myocardium develops cardiomyopathy or myocarditis when exposed to stresses or infection." (PMID 33928132, 2021). "Indeed, mutations in BAG3, a critical proteostatic mediator in cardiac myocytes induce cardiomyopathy without formation of protein aggregates, likely because BAG3 is required for aggregate formation." (PMID 32581848, 2020). "Overall, lead variants at 9 of the 61 GWS loci were located nearest to known cardiomyopathy genes (ACTN2, ALPK3, BAG3, FLNC, PLN, TTN), representing significant enrichment (hypergeometric p = 6.01 × 10−11)." (PMID 36376295, 2022). "BAG3, probably the most studied BAG family member, plays a role in neurodegenerative diseases, viral infections, cardiomyopathy, and cancer." (PMID 35203329, 2022). "Together, these data suggest that injection of a predicted MMEJ-inducing sgRNA targeting dnajb6b was able to recapitulate many but not all modifying effects of GBT411/dnajb6b on bag3 cardiomyopathy." (PMID 35481478, 2023).
cardiomyopathy (continued). "In our prior genetic analysis of the UK Biobank, we refined a heterogeneous heart failure phenotype to a specific, nonischemic cardiomyopathy subset, enabling detection of two DCM risk loci (near BAG3 and CLCNKA) that associated with subclinical changes in LV structure and function." (PMID 32382064, 2020). "Although repairing defective proteostasis could be a plausible therapeutic strategy, no target genes have yet been reported for BAG3 cardiomyopathy." (PMID 31492659, 2019).
dilated cardiomyopathy (41 papers, 2014 to 2025). Cardiomyopathy which is characterized by dilation and contractile dysfunction of the left and right ventricles. "Approximately 15% of dilated cardiomyopathy (DCM) cases are associated with Bcl2-associated athanogene 3 (BAG3) gene mutations, which play a crucial role in myofilament organization and contractile behavior." (PMID 41328308, 2025). "BAG3 has been recently identified as a causative gene for dilated cardiomyopathies (DCM), which is characterized by ventricular chamber enlargement and systolic dysfunction." (PMID 40922543, 2025). "Loss-of-function variants of BAG3 leading to decreased BAG3 levels were associated with dilated cardiomyopathy." (PMID 40756361, 2025). "Previous research on BAG3 mostly focused on the correlation between BAG3 mutation and genetic diseases such as dilated cardiomyopathy." (PMID 38664681, 2024). "Instead, the dilated cardiomyopathy-related BAG3 p.E455K, which also affects the BAG domain, causes a decrease in the interaction with HSPA and likely affects CASA activity and proteostasis through a different mechanism." (PMID 36594740, 2023). "Genetic testing revealed a rare BCL2-associated athanogene 3 (BAG3) variant associated with dilated cardiomyopathy." (PMID 37216087, 2023). "In a group of similarly large GWAS studies, the BAG3 locus was associated with dilated cardiomyopathy." (PMID 36980278, 2023). "In contrast, several variants and mutations in BAG3 have been associated with diseases, primarily dilated cardiomyopathy, but also myopathy and neuropathy." (PMID 36594740, 2023). "For example, myocardial tissue from patients with dilated cardiomyopathy has increased levels of myofibrillar ubiquitination associated with dysfunctional protein degradation through autophagy via the co‐chaperone BAG3." (PMID 35262277, 2022). "Evidence in recent years indicates an essential role for BAG3 in the heart with numerous clinical studies finding that BAG3 mutations are associated with dilated cardiomyopathy (DCM) and myofibrillar myopathy." (PMID 34011988, 2021). "Three missense mutations targeting the same proline 209 (Pro209) codon in the co-chaperone Bcl2-associated athanogene 3 (BAG3) have been reported to cause distal myopathy, dilated cardiomyopathy or Charcot-Marie-Tooth type 2 neuropathy." (PMID 32472079, 2020). "Mutations in the Bag3 gene are described to cause a diverse spectrum of disease phenotypes including striated muscle diseases such as dilated cardiomyopathy (DCM) or myofibrillar myopathy (MFM)." (PMID 33137814, 2020). "Although patients with CCM had rare variants in several established dilated cardiomyopathy (DCM) genes (BAG3, LMNA, MYH7, TCAP, TNNT2, and TTN), only variants in TTN, which encodes titin, were significantly increased." (PMID 30987448, 2019). "A GWAS identified association of BAG3 with dilated cardiomyopathy, and suggestive association with alcohol dependence." (PMID 29912962, 2018). "Mutations in the bag3 gene are associated with the development of severe diseases, such as myofibrillar myopathy or dilated cardiomyopathy (see Impact of BAG3 on Myopathies)." (PMID 28680391, 2017). "More recently, we found a 10 nucleotide mutation in exon 6 of the BAG3 gene in a large family with familial dilated cardiomyopathy." (PMID 25925243, 2015). "Loss of Bcl2-associated athanogene 3 (BAG3) is associated with dilated cardiomyopathy (DCM)." (PMID 39744939, 2025). "Dominant mutations in BCL2-associated athanogene 3 (BAG3) cause a rapidly progressive childhood- or adolescence-onset myofibrillar myopathy with limb and axial weakness, peripheral neuropathy, respiratory failure and a severe dilated cardiomyopathy." (PMID 39501809, 2024). "In addition to the known missense variant (rs2234962) in the BAG3 locus for dilated cardiomyopathy, we identify deleterious or damaging protein-coding variants in genes SYNPO2L, ERBB2, and STARD3 in strong LD with sentinel SNPs (LD R2 > 0.8)." (PMID 36517512, 2022).
dilated cardiomyopathy (continued). "BAG3 gene mutations have been recently implicated as a novel cause of dilated cardiomyopathy (DCM)." (PMID 25008357, 2014). "Here, we studied whether a clinical association between BAG3-related FDCM and circulating miRNAs may have diagnostic and prognostic value in a small cohort of familial related individuals carrying a BAG3 mutation (BAG3+) and/or diagnosed of dilated cardiomyopathy (DCM) (DCM+)." (PMID 30792263, 2019). "Moreover, other mutations of the bag3 gene, for instance Arg218Trp, Leu462Pro, a 10-nucleotide mutation in exon 4 or a deletion of exon 4 of bag3, were reported to be causative of (familial) dilated cardiomyopathy (DCM)." (PMID 28680391, 2017). "BAG3 is a key candidate gene in dilated cardiomyopathy (DCM) cases, including peripartum DCM, cardiotoxicity from chemotherapy, and myocarditis, and is linked to tumor growth." (PMID 41378130, 2025). "Previous studies have indicated that BAG3 plays an essential role in various cardiovascular diseases (CVDs), such as myocardial hypertrophy, dilated cardiomyopathy and chronic heart failure." (PMID 35893075, 2022). "Previous studies have indicated that BAG3 is involved in various cardiovascular diseases, such as myocardial hypertrophy, dilated cardiomyopathy, and chronic heart failure." (PMID 35893075, 2022). "Both BAG3 and TTN contribute to the function of the contractile apparatus in cardiomyocytes, and rare deleterious variations cause Mendelian forms of dilated cardiomyopathy." (PMID 35132965, 2022). "In humans, mutations in BAG3 (Bcl2-associated athanogene 3) were found to cause dilated cardiomyopathy (DCM) and myofibrillar myopathies (MFM); however, the molecular BAG3-associated underpinnings are poorly understood." (PMID 33137814, 2020). "The variants in the CLCNKA and BAG3 loci for LVEF and LVESV were associated with dilated cardiomyopathy (DCM) (Table XI in the online-only Data Supplement)." (PMID 31554410, 2019). "Mutations in BAG3 are associated with a devastating syndrome that includes MFM, dilated cardiomyopathy, and neuropathy." (PMID 30559338, 2018). "Dilated cardiomyopathy (DCM) of case 2 may be related to AMA positivity as reported, but the BAG3 mutation may also cause DCM." (PMID 38566087, 2024). "A multicohort study found an association between Bcl2-associated anthanogene 3 (BAG3) and negative outcome in cases of dilated cardiomyopathy in African Americans." (PMID 37190244, 2023). "For example, some genetic variants were included in the MR analyses which could be more specific for another trait (i.e. rs2234962 near BAG3 for dilated cardiomyopathy)." (PMID 37532724, 2023). "A previous study showed that BAG3 deletion could eliminate Hsp22 expression due to structural instability, leading to dilated cardiomyopathy (DCM)." (PMID 34679684, 2021). "The first suggestion that BAG3 could play a role in adult-onset familial dilated cardiomyopathy came from a study of patients with a dilated cardiomyopathy, diffuse myocardial fibrosis and sudden death." (PMID 25925243, 2015). "Several other BAG3 mutations were found in early- and late onset dilated cardiomyopathy (DCM) patients without the obvious skeletal muscle phenotype." (PMID 26545904, 2015). "Genetic mutations contribute to 30-40% of dilated cardiomyopathy (DCM) and HCM cases, with titin truncating variant (TTNtv), myosin-binding protein C3 (MYBPC3), lamin A/C gene (LMNA) and BCL2-associated athanogene-3 (BAG3) among the most common pathogenic variants." (PMID 40313442, 2025). "Although the pathogenicity of several dilated cardiomyopathy variants might be questioned based on the absence of functional studies, a few BAG3 mutations have been deeply investigated in cell and animal models." (PMID 36594740, 2023).
dilated cardiomyopathy (continued). "The study found four BAG3 variants which were not present in a reference population of European ancestry that were associated with a significantly increased hazard ratio in African Americans with dilated cardiomyopathy (HR, 1.97; 95% CI, 1.19–3.24)." (PMID 37190244, 2023). "The relevance of BAG3 in the etiology of dilated cardiomyopathy (DCM) arise from studies in which the levels of BAG3 in the heart of patients with advance heart failure were significantly reduced, suggesting that BAG3 may represent a critical component to prevent heart failure." (PMID 30792263, 2019). "We describe a case of concurrent FD, IgAN, and dilated cardiomyopathy-causing mutations in the TTN and BAG3 genes, which has not been reported previously." (PMID 37914990, 2023). "Thus, it becomes relevant to understand the cellular biology and molecular regulation of BAG3 expression in order to design new therapies for the treatment of patients with both hereditary and non-hereditary forms of dilated cardiomyopathy." (PMID 25925243, 2015).